MIF (macrophage migration inhibitory factor)
Diseases named in the same sentence as MIF in open-access papers (continued):
Sharing a sentence is not in itself a finding about the gene and the disease.
diabetes (57 papers, 2011 to 2026). "Recent studies have reinforced the evidence of an association between MIF and diabetes-related clinical complications, such as neuropathy, nephropathy, and retinopathy." (PMID 34445689, 2021). "To explore the potential of MIF gene variation, we established a nomogram composed of MIF rs2070766 genotypes, diabetes, WBC, TC and HDL-C to predict the risk of ACS." (PMID 35046995, 2021). "More recently, MIF was proposed as a diagnostic biomarker for autoimmune diseases such as arthritis, ulcerative colitis, and diabetes." (PMID 24527464, 2014). "Impaired β cell function, along with the impact of PDAC-released factors (e.g., adrenomedullin (ADM), IGF-1, and macrophage inhibitory factor (MIF) on pancreatic islets, may contribute to the induction of diabetes associated with PDAC." (PMID 39596226, 2024). "Finally, there is an association of MIF with depression at the genetic level: women with type 2 diabetes mellitus carrying the rs755622 C allele within the MIF gene presented a higher risk of depression." (PMID 36555097, 2022). "MIF is an important mediator in the development of diabetes and various associated complications." (PMID 34445689, 2021). "In our study, the cardiac protective role of MIF could be limited because of the myocardial damage caused by stress hyperglycemia or diabetes." (PMID 30983881, 2019). "The sharp increase in MIF levels in the circulating blood after myocardial infarction may conceal the increased MIF levels caused by diabetes." (PMID 30983881, 2019). "In T1D, the pathogenic contribution of MIF was reported by studies demonstrating that antibody and pharmacological inhibitor-mediated MIF neutralization had a prophylactic effect on accelerated diabetes models." (PMID 29095944, 2017). "A different MIF genotype (rs755622GC) was shown to be associated with baseline diabetes in men but not in women in a population-based cohort study in Turkish subjects, and carriage of the C-allele tended to predict new-onset diabetes in this population." (PMID 26124760, 2015). "To date, MIF has been implicated in both types of diabetes; therefore, understanding the role of MIF could affect our understanding of the autoimmune or inflammatory responses that influence diabetic pathology." (PMID 24527464, 2014). "Interestingly, recent studies demonstrated that coxsackievirus B3-induced myocarditis as well as human diabetes-linked LV dysfunction correlate with increased MIF concentration in the bloodstream." (PMID 23451183, 2013). "In addition, MIF rs755622 might interact with diabetes or hypercholesterolemia in increasing susceptibility to ESRD." (PMID 35205271, 2022). "Furthermore, development of multiple low-dose streptozotocin (MLD-STZ)-induced diabetes could be suppressed in mice deficient for MIF, suggesting that MIF is a key player in the development of immune-mediated diabetes." (PMID 29095944, 2017). "Furthermore, increased plasma levels of MIF were identified as a risk factor for increased heart failure in CHD patients with impaired glucose tolerance or type 2 diabetes mellitus, and were associated with inflammatory marker expression in patients with acute coronary syndrome (ACS)." (PMID 23720662, 2013). "MIF is also highly expressed in diabetes complications such as myocardial damage, coronary artery disease and diabetic retinopathy, suggesting a graded increase in circulating MIF with disease severity." (PMID 39717018, 2025). "As a major source of cytokines, including MIF, macrophages play an important role in chronic inflammation in diabetes." (PMID 39717018, 2025). "Among candidate loci, the macrophage migration inhibitory factor (MIF) gene and the ARAP1 locus have been implicated in diabetes-related traits." (PMID 41036138, 2025). "All these molecules, excluding MIF, demonstrated significant associations with TIR ≤ 70% after adjustments for age, sex, BMI, diabetes duration, and eGFR." (PMID 37893217, 2023).
diabetes (continued). "Recently, several MIF inhibitors/antagonists have been developed and have been shown to have therapeutic effects on several experimental disease models including diabetes, bone disease, and cancer." (PMID 35563296, 2022). "According to the method described in statistical section, using MIF rs2070766 genotypes and clinical variables (diabetes, WBC, TC and HDL-C), we developed a nomogram model to predict risk of ACS." (PMID 35046995, 2021). "Ample evidence shows that MIF is involved in the regulation of heart function under pathological conditions, including burns, diabetes and I/RI." (PMID 33692685, 2020). "Our study results suggest that MIF further affects patient survival with myocardial ischemia and myocardial fibrosis after myocardial infarction by participating in myocardial inflammation caused by hyperglycemia and diabetes, which may be related to the long-term prognosis of patients." (PMID 30983881, 2019). "We also evaluated circulating MIF concentrations at different disease stages in diabetes-prone NOD mice." (PMID 29095944, 2017). "Macrophage migration inhibitory factor (Mif) is highly expressed in type 1 diabetes mellitus (T1DM)." (PMID 27699180, 2016). "High plasma MIF levels have also been identified as an independent risk factor for future coronary events in patients with CVD and impaired glucose tolerance or type 2 diabetes mellitus." (PMID 26257740, 2015). "Since MIF showed a dual regulation activity on inflammatory and metabolic effects, it represents a logical focus of study in the field of diabetes." (PMID 24708788, 2014). "We will discuss the data that have been collected in clinical studies and studies of MIF-KO mice and other protocols in which MIF has been proposed as a therapeutic diabetes mellitus pathological target." (PMID 24527464, 2014). "In this type of diabetes, MIF has been suggested to contribute to the disease in an indirect form due to its ability to stimulate the production of other inflammatory cytokines that directly cause damage to muscle cells." (PMID 24527464, 2014). "This review highlights our current knowledge about the involvement of MIF in both types of diabetes in the clinical environment and in experimental disease models." (PMID 24527464, 2014). "MIF has been shown to enhance beta cell destruction in mice and to increase diabetes incidence in NOD mice." (PMID 24023664, 2013). "Compared with healthy subjects, patients with diabetes have significantly increased levels of plasma MIF which was further increased in diabetic patients with Left ventricular diastolic dysfunction (LVDD)." (PMID 21283592, 2011). "MIF is thus a potential therapeutic target for diabetes‐induced tendinopathy." (PMID 40896276, 2025). "Additionally, macrophage migration inhibitory factor (MIF), an important regulator in diabetes pathogenesis, enhances the osteochondrogenic differentiation of TSPCs while inhibiting their tendonogenic differentiation, as noted by Kim." (PMID 40896276, 2025). "Taken together, this suggests that pharmacological AMPK activation could be a strategy for reducing macrophage MIF release in diseases such as diabetes, where glucose variation frequently occurs." (PMID 39717018, 2025). "Therefore, it is possible that FTX is involved in the inflammatory response in diabetes through MIF." (PMID 36874406, 2023). "Therefore, in this study, we aimed to confirm the harmful effects of diabetes on tendon homeostasis and to clarify the effect of MIF on the differentiation potential and tendon homeostasis of TdSCs under hyperglycemic conditions." (PMID 34445689, 2021). "In the previous report, we showed that under diabetic conditions, MIF could aggravate diabetic neuropathic pain, and MIF over-expression was accompanied by low expression of GLO-1 and IENF in the foot pad of hind paw." (PMID 32591628, 2020).
diabetes (continued). "Therefore, further large-scale investigations and careful comparisons are required to confirm the predictive ability of MIF in the long-term prognosis in patients with acute myocardial infarction complicated with diabetes." (PMID 30983881, 2019). "In addition, we have found that diabetes down-regulated the RNA expression of MIF genes both one and seven days after incision in comparison to the control samples under the present investigation." (PMID 26498022, 2015). "Indeed, two candidate drugs (synthetic inhibitors for MIF) for diabetes treatment were described as very effective in the control of the systemic inflammation and the control of some diabetes symptoms." (PMID 24527464, 2014). "Several clinical and basic evidences support a relationship MIF level and diabetes." (PMID 24708788, 2014). "We support the statement that MIF is a therapeutic target and propose that it is necessary to design synthetic MIF inhibitors that could interact with the existing therapies used to treat diabetes." (PMID 24527464, 2014). "Because it remains unclear whether diabetes confounds the function of urinary MIF in detecting AKI, we analyzed the level of urinary MIF in diabetic patients." (PMID 23319831, 2012). "Therefore, MIF may play a role in modulating diabetes progression and limiting inflammatory strength." (PMID 39851524, 2025). "To identify whether MIF affects tendon homeostasis in diabetes, we designed an in vitro experimental model using TdSCs harvested from the Achilles tendon of healthy SD rats and assessed changes in differentiation potential with MIF exposure in experimental hyperglycemic conditions." (PMID 34445689, 2021). "If we could show that knockdown MIF has a beneficial effect on osteochondrogenic and tenogenic differentiation of the TdSCs isolated from diabetic rats, that would be a strong evidence for arguing that MIF has a role in the pathogenesis of the tendon defect in those with diabetes." (PMID 34445689, 2021). "In addition, MIF has been identified as an important regulator of the pathogenesis of diabetes." (PMID 34445689, 2021). "Despite the compelling evidence suggesting MIF play role in cancer and diabetes, there is no data whether MIF could promote PC associated diabetes (PCDM) and distinguish it from T2DM." (PMID 24708788, 2014). "In the present study, we show that MIF is overexpressed in human PC tissue, especially in tissues of patients with new-onset diabetes, and is found elevated in the blood of new-onset DM PC patients." (PMID 24708788, 2014). "Actually, MIF might be involved in diabetes pathogenesis in much more ways: regulation the insulin secretion, modulation inflammation such as exacerbates insulitis and local pancreatic inflammation, contribute to beta cell apoptosis in cooperate with other toxics." (PMID 24708788, 2014). "We sought to examine the mechanistic role of AMPK in low glucose‐induced changes in the pro‐inflammatory cytokine macrophage migration inhibitory factor (MIF), which is elevated in people with diabetes." (PMID 39717018, 2025). "In the non-MetS group, patients with the high-MIF level (≥ 143 ng/ml) had a greater incidence of diabetes and MACCE than those with the low-MIF level (< 143 ng/ml, both P < 0.05)." (PMID 36035926, 2022). "Macrophage migration factor (MIF) and matrix metalloproteinase (MMP-9) are the most important factors in the pathogenesis of diabetes." (PMID 34567195, 2021). "Macrophage migration factor (MIF) and matrix metalloproteinase (MMP-9) are two of the most important factors in the pathogenesis of diabetes." (PMID 34567195, 2021). "The hyperglycemic environment of diabetes mellitus activates inflammatory cells and increases the production of reactive oxygen species (ROS) and pro-inflammatory cytokines (e.g., IL-6, TNF-α, macrophage migration inhibitory factor (MIF), etc.)." (PMID 38672083, 2024).
diabetes (continued). "Among subjects with diabetes, those with TIR ≤ 70% had higher levels of IL-1α, IL-1β, IL-6, IL-12 p70, IL-16, LIF, M-CSF, MCP-1, MCP-3, RANTES, TNF-α, TNF-β, and b-NGF, and lower levels of IL-1α, IL-4, IL-10, GM-CSF, and MIF than individuals with TIR > 70%." (PMID 37893217, 2023). "Although the role of MIF in T1DM development has already been reported, none of them have reported an upregulation of MIF in peritoneal immune cells during early diabetes induction." (PMID 36875761, 2023). "The oral administration of a small-molecule MIF antagonist, CPSI-1306, can also significantly lower blood glucose levels and inhibit proinflammatory cytokines IL-6 and TNF-α expression in a mouse model of streptozotocin-induced diabetes." (PMID 35563296, 2022). "In patients with acute myocardial infarction with or without diabetes, early blood MIF levels can reflect the extent of impaired cardiac function in the acute phase." (PMID 30983881, 2019). "In STEMI patients without diabetes, MIF levels can also indicate cardiac function and long-term prognosis at the 12-month follow-up." (PMID 30983881, 2019). "In view of the previous suggestion that plasma MIF levels are significantly higher in patients with type 2 diabetes than in healthy people, we further compared plasma MIF levels in STEMI patients with or without diabetes mellitus." (PMID 30983881, 2019). "Plasma MIF levels in the diabetes and nondiabetes STEMI group were positively correlated with the extent of acute cardiac function impairment, including Killip grade ≥ II, LVEF, and LVDD acute phase." (PMID 30983881, 2019). "In patients with acute myocardial infarction without diabetes, MIF levels can predict cardiac function and long-term prognosis at the 12-month follow-up." (PMID 30983881, 2019). "It was reported that patients with coronary heart disease and diabetes have higher blood MIF levels than nondiabetes patients with coronary heart disease." (PMID 30983881, 2019). "In order to evaluate the potential in vivo relevance of MIF/CD74 pathway during T1D, we investigated whether targeting MIF could prevent diabetes transfer by autoimmune NOD splenocytes into NOD.SCID mice." (PMID 29095944, 2017). "However, RT-PCR analysis of locally wounded skin tissues revealed that diabetes down-regulates the RNA expression of both TNF-α and MIF genes in comparison to the control samples but that CMP was found to restore RNA expression significantly." (PMID 26498022, 2015). "For example, the expression of MIF is increased in both pancreatic beta cells and peripheral lymphocytes of mice with autoimmune diabetes, in addition, in NOD mice treated with rMIF the incidence of diabetes is increased from 55% to 86%." (PMID 24708788, 2014). "However, a few studies on the relationship between MIF and HDC in other diseases (e.g., cancer, parasitic infections, and diabetes) determined that the MIF/CD74 signaling pathway regulates the functional status of DCs, but the regulation capacity varies greatly." (PMID 37102665, 2023). "However, one must consider that diabetes is also an inflammation state, and non-specific inflammatory parameters like MIF or CXCL12 can be elevated in patients with IHD or without it." (PMID 35663309, 2022). "Plasma MIF levels of patients in the diabetes and nondiabetes STEMI groups were negatively correlated with LVEF within 72 h of admission (r = −0.336 and r = −0.365, respectively, both P < 0.01) but were positively correlated with LVDD (r = 0.198, r = 0.301, all P < 0.05)." (PMID 30983881, 2019). "However, plasma MIF levels were positively correlated with hs-TnT peak values in the diabetes and nondiabetes STEMI groups (r = 0.343 and r = 0.474, respectively, both P < 0.01)." (PMID 30983881, 2019). "Plasma MIF levels in patients were not correlated with age (r = 0.205, r = 0.067, both P > 0.05), eGFR (r = −0.020, r = −0.037, P > 0.05), or HbAlc (r = 0.122, r = 0.106, both P > 0.05) in either the diabetes STEMI or nondiabetes STEMI groups." (PMID 30983881, 2019).
diabetes (continued). "Thus, MIF levels in STEMI patients with or without diabetes can reflect acute cardiac function." (PMID 30983881, 2019). "Furthermore, it remains unclear whether the protection against disease onset by targeting MIF in these cases was not merely a result of dampening the acute inflammatory events triggered by the diabetes-inducing/accelerating chemical agents." (PMID 29095944, 2017). "The present study evaluates the levels of MIF and MMP-9 in non-diabetics in the families with family members who have type 2 diabetes mellitus." (PMID 34567195, 2021). "This study is aimed at investigating the correlation between plasma MIF levels and cardiac function and prognosis in patients with acute ST-segment elevation myocardial infarction (STEMI) with or without diabetes mellitus." (PMID 30983881, 2019). "In this study, plasma MIF levels were significantly higher in STEMI patients with and without diabetes than in healthy control individuals and nondiabetes STEMI patients with stress hyperglycemia had higher MIF levels than those with euglycemia." (PMID 30983881, 2019). "In contrast, MIF expression was significantly reduced in T2DM-DF compared to ND-DF (58.7 ± 12.3 vs 280.4 ± 126.2% GAPDH; P = 0.0016 for effect of diabetes, two-way ANOVA, n = 4), while TNF-α had no modulatory effect in either (P = 0.7303 for effect of TNF-α, two-way ANOVA, n = 4)." (PMID 33446687, 2021).